ERO1B (endoplasmic reticulum oxidoreductase 1 beta)
Description:
Oxidoreductase involved in disulfide bond formation in the endoplasmic reticulum. Efficiently reoxidizes P4HB/PDI, the enzyme catalyzing protein disulfide formation, in order to allow P4HB to sustain additional rounds of disulfide formation. Other protein disulfide isomerase family members can also be reoxidized, but at lower rates compared to P4HB, including PDIA2 (50% of P4HB reoxidation rate), as well as PDIA3, PDIA4, PDIA6 and NXNDC12 (<10%). Following P4HB reoxidation, passes its electrons to molecular oxygen via FAD, leading to the production of reactive oxygen species (ROS) in the cell. May be involved in oxidative proinsulin folding in pancreatic cells, hence may play a role in glucose homeostasis.
Synonyms: ERO1LB; ERO1-L(beta); Ero1beta
Tractability: Antibody: UniProt places it where antibodies can reach, with high confidence; UniProt predicts a signal peptide or a membrane-spanning region.
Gene: Protein-coding gene on chromosome 1 (236,214,681 to 236,282,019, reverse strand). Ensembl gene ENSG00000086619.
Subcellular location: Endoplasmic reticulum membrane
Pathways (Reactome):
Metabolism of proteins: Insulin processing
Gene Ontology:
Molecular function: flavin-dependent sulfhydryl oxidase activity; protein binding; protein-disulfide reductase activity; thiol oxidase activity; oxidoreductase activity; disulfide oxidoreductase activity; FAD binding
Biological process: protein folding in endoplasmic reticulum; insulin processing; protein folding
Cellular component: endoplasmic reticulum; endoplasmic reticulum lumen; endoplasmic reticulum membrane; membrane
Genetic constraint (gnomAD): Loss-of-function variants: 25 observed, 41.8 expected, observed/expected ratio (o/e) 0.6, 90% interval 0.44 to 0.83. The upper end of that interval is the gene's LOEUF score, 0.83, which puts it in group 3 of 6, group 1 being the genes least tolerant of losing a copy. Missense variants: 342 observed, 364.69 expected, observed/expected ratio (o/e) 0.94, 90% interval 0.86 to 1.03. Synonymous variants: 142 observed, 127.17 expected, observed/expected ratio (o/e) 1.12, 90% interval 0.97 to 1.28.
Homologues: Orthologues: chimpanzee ERO1B (99% identical), macaque ERO1B (99% identical), dog ERO1B (96% identical), guinea pig ERO1B (96% identical), pig ERO1B (96% identical), mouse Ero1b (94% identical), rat Ero1b (92% identical), rabbit ERO1B (85% identical), tropical clawed frog ero1b (80% identical), zebrafish ero1b (75% identical), Drosophila melanogaster Ero1L (46% identical), Caenorhabditis elegans ero-1 (41% identical). Paralogues in human: ERO1A (61% identical).
Diseases named in the same sentence as ERO1B in open-access papers:
ERO1B is named in the same sentence as 19 diseases in open-access papers, as found by Europe PMC text mining. Sharing a sentence is not in itself a finding about the gene and the disease. The quoted sentences say what the papers report.
diabetes (4 papers, 2016 to 2025). "It is hypothesized that decreased ERO1β expression might contribute to the progression of diabetes and β-cell dysfunction by exacerbating ER stress." (PMID 40109403, 2025). "Whether PRDX4 hyperoxidation in diabetes models is due to excess ERO1β activity is not known, but ERO1β overexpression promotes ER hyperoxidation, which consequently leads to inactivation of PRDX4." (PMID 40136648, 2025).
pancreatic cancer (3 papers, 2017 to 2022). "In relation to lung cancer, ERO1B has been recently identified as a gene that, together with an additional three genes identified using TCGA LUAD dataset, is able to predict patient prognosis and has been suggested to be a biomarker for pancreatic cancer." (PMID 32235589, 2020).
esophageal cancer (1 paper, 2022). A primary or metastatic malignant neoplasm involving the esophagus. "Another study showed ERO1B was one of the prognostic indicators of esophageal cancer (EC)." (PMID 36552760, 2022).
glioma (1 paper, 2022). A benign or malignant brain and spinal cord tumor that arises from glial cells (astrocytes, oligodendrocytes, ependymal cells). "In addition, we explored the proteins expressed by REEP6, LARP4B, CWC27, GOLGA2, ATP6AP1 and ERO1B in glioma patients through the HPA database, and REEP6, LARP4B, GOLGA2 and ATP6AP1 showed higher staining intensity in glioma than in normal brain tissue." (PMID 36552760, 2022).
Hyperglycemia (1 paper, 2025). An increased concentration of glucose in the blood. "Loss of ERO1β resulted in the accumulation of misfolded proinsulin, reduced islet insulin content, and hyperglycemia in mice." (PMID 40136648, 2025). "For example, ERO1β overexpression significantly increased ER hydrogen peroxide content and led to impaired insulin secretion and hyperglycemia in a mouse model." (PMID 40136648, 2025).
cancer (5 papers, 2020 to 2025). A tumor composed of atypical neoplastic, often pleomorphic cells that invade other tissues. "Bioinformatics analyses showed that the expression levels of six out of 25 genes (ERO1B, DPY19L1, NCAM1, RET, MARCH1, and SLC7A8) were associated with LUAD patient survival (p < 0.05), and pathway analyses indicated that major cancer signaling was altered in the subtypes." (PMID 32235589, 2020).
tumor (5 papers, 2016 to 2025). "In univariate analysis, clinical characteristics (gender, age, T, N, M and tumor stage), APOA2, COX6A2, HIST1H1E, UBE2C, ERO1B and eight gene comprehensive risk scores were prognostic risk factors for patients with the EC (P < 0.05)." (PMID 35568702, 2022). "(A) mRNA expression of ER-stress markers Edem1, Ero1b, Grp94, Herp, Atf4, Eif2ak3, Ddit3, and Hspa5 in liver tissue from healthy mice; and tumor tissue and surrounding non-tumoral tissue from mice with DEN-induced HCC." (PMID 33103995, 2020).
ERO1B also shares sentences with these, for which no sentence is quoted: lung adenocarcinoma (2 papers); pancreatic neuroendocrine tumor (2); breast carcinoma (1); cardiovascular diseases (1); COVID-19 (1); gastric cancer (1); Hypercholesterolemia (1); lung carcinoma (1); lymph node metastasis (1); neurodegenerative disease (1); pancreatic adenocarcinoma (1); Type 2 Diabetes (1).